OAS3 (2'-5'-oligoadenylate synthetase 3)
Diseases named in the same sentence as OAS3 in open-access papers (continued):
Sharing a sentence is not in itself a finding about the gene and the disease.
cancer (15 papers, 2010 to 2026). A tumor composed of atypical neoplastic, often pleomorphic cells that invade other tissues. "Survival analysis revealed that high OAS3 expression was significantly associated with unfavorable prognosis in several cancers." (PMID 41700140, 2026). "Previous studies have reported that OAS genes, particularly OAS1 and OAS3, are often involved in antiviral responses and immune regulation but have not been extensively studied for their mutational frequency in cancers." (PMID 39633486, 2024). "In previous studies, OAS3 has been reported as a risk factor for different cancers, which is consistent with the results of this study." (PMID 35592250, 2022). "The findings suggest that OAS3 is closely associated with the development of various systemic diseases and cancers." (PMID 35592250, 2022). "From each region, the single most significant SNPs associated with CIN3/cancer were OAS3 rs12302655, SULF1 rs4737999, IFNG rs11177074, DUT rs3784621, DMC1 rs5757133, GTF2H4 rs2894054, EVER1/EVER2 rs9893818 (p-trends≤0.001)." (PMID 20084279, 2010). "In addition, OAS3 expression is associated with the prognosis and chemotherapeutic outcomes of various cancers." (PMID 35592250, 2022). "We found that cancer cells with lower levels of Lsd1 or higher levels of Oas1 or Oas3 were significantly more dependent on CFLAR." (PMID 38280853, 2024). "Among the enriched CCs, The cytoplasm (associated with 6 KGs: OAS1, OAS3, IRF9, HPGD, TP53INP1 and NQO1) has been found to be associated with most proteins that are highly expressed for cancer." (PMID 35617355, 2022). "In diverse cancer types, the correlation between OAS3 and the expression of checkpoint genes indicated a high correlation with TNF-related immune genes including TNFRSF14, TNFRSF8, TNFRSF25, TNFRSF4, TNFRSF18, TNFSF15, and TNFRSF9." (PMID 35592250, 2022). "Immune scores, ESTIMATEScore and stromal scores were significantly correlated with OAS3 expression in 20, 25, and 20 of the 33 cancers, respectively." (PMID 35592250, 2022). "In this study, OAS3 expression was positively correlated with 47 immune checkpoint genes in most cancer types." (PMID 35592250, 2022). "The evidence for the significant immunological utility of OAS3 as a prognostic and immunotherapeutic biomarker for pan-cancer provides compelling new insights into the potential development of future immunotherapeutic and diagnostic trials." (PMID 35592250, 2022). "In this study, we performed an integrative analysis of molecular characteristics, oncogenic roles and relevant immune and pharmacogenomic features of OAS3 in pan-cancer." (PMID 35592250, 2022). "SNPs for OAS3, SULF1, DUT, and GTF2H4 were associated with HPV persistence whereas IFNG and EVER1/EVER2 SNPs were associated with progression to CIN3/cancer." (PMID 20084279, 2010). "However, when the GTEx and TCGA data were combined, the difference was significant among 29 of the 33 cancers, and OAS3 expression was lower in KICH than in normal tissues." (PMID 35592250, 2022). "In addition, the expression of OAS3 was higher in various cancer cell lines in the Cancer Cell Line Encyclopedia (CCLE) database than in normal tissue." (PMID 35592250, 2022). "Furthermore, we investigated the relationship between OAS3 expression and the prognosis of 33 cancers." (PMID 35592250, 2022). "Therefore, OAS3 can be used as a novel drug target for anti-cancer immunotherapy." (PMID 35592250, 2022). "Based on the findings of this study, OAS3 expression is positively correlated with MMR-related genes, RNA methylation and four DNA methyltransferases in most cancers." (PMID 35592250, 2022). "Rs4801778-T (PLEKHA4), rs11919389-C (ZBTB11), rs13050728-C (IFNAR2), and rs10774671-A (OAS1) exhibited a positive or negative regulation in TULP2, HSD17B14, LOC285359, LOC100009676, SENP7, IFNAR2, OAS3, and OAS1 in multiple cancer types." (PMID 35082790, 2021).
cancer (continued). "In addition, OAS3 was positively correlated with four major DNA methyltransferases including DNMT1, DNMT2, DNMT3A, and DNMT3B in most cancer types." (PMID 35592250, 2022).
bacterial infection (2 papers, 2022 to 2025). "When comparing gene expression in viral versus bacterial infection, five classifier genes (OAS3, IFI27, USP18, DSC2, RSP21) were significantly differentially expressed." (PMID 41496780, 2025). "We showed that the median expression of certain genes (IFI27, HLA-DRB1, USP18, STAP1, and OAS3) in the Biomeme HR-B/V classifier was higher in viral versus bacterial infection." (PMID 41496780, 2025).
cardiovascular disease (1 paper, 2021). "OAS3 is one of the key antiviral factors induced by IFN, but it is also related to some characteristic factors of cardiovascular disease." (PMID 34447459, 2021).
infectious disease (1 paper, 2017). A disorder directly resulting from the presence and activity of a microbial, viral, or parasitic agent in humans. "Notably, three genes, OAS1, OAS2, and OAS3 of the 2'-5'-oligoadenylate synthetase family, were significantly up-regulated in T2DM and presented in all of these infectious disease pathways." (PMID 28427244, 2017).
inflammatory myopathies (1 paper, 2023). "Using microarrays, IFIG expression levels (including ISG5, Mx1, OAS1, IFIT4, IFIT1, IFI44, OAS3, OAS2, IRF7, and IFI27) in muscle samples were higher in DM than in other inflammatory myopathies, such as inclusion body myositis, polymyositis, necrotizing myopathy, and myopathies with inflammation." (PMID 36979843, 2023).
renal disorders (1 paper, 2020). "Active SLE patients with renal disorders showed higher OAS2 and OASL expression in PBMCs, OAS3 and OASL expression in CD19+ B cells, and OAS3 expression in CD4+ T cells than patients without the symptoms (P<0.05)." (PMID 32321151, 2020).
OAS3 also shares sentences with these, for which no sentence is quoted: systemic lupus erythematosus (4 papers); Epstein-Barr virus infection (2); acute lung injury (1); alcohol dependence (1); asthma (1); cervical intraepithelial neoplasia (1); diabetic (1); endometrial cancer (1); epileptic seizures (1); hepatitis E virus infection (1); hepatoma (1); hypospadias (1); lung (1); nonalcoholic fatty liver disease (1); pancreatic adenocarcinoma (1); pneumonia (1); psoriasis vulgaris (1); sarcoidosis (1); SARS-CoV infection (1); sweet syndrome (1); testicular dysgenesis syndrome (1); tick-borne encephalitis (1); type 1 diabetes (1); type 2 diabetes (1); viral diseases (1); vitiligo (1).